ESRRA (estrogen related receptor alpha)
Diseases named in the same sentence as ESRRA in open-access papers (continued):
Sharing a sentence is not in itself a finding about the gene and the disease.
osteosarcoma (14 papers, 2014 to 2025). A usually aggressive malignant bone-forming mesenchymal neoplasm, predominantly affecting adolescents and young adults. "For example, IGF2BP1-stabilized estrogen-related receptor alpha (ERRα) mRNA is involved in metabolic reprogramming of chemoresistant osteosarcoma cells." (PMID 40592832, 2025). "On the other hand, ESRRA also exerts repression effect on SPP1 promoter transactivation in human osteosarcoma cell lines SaOs-2 and U2-OS by cross-talking with another nuclear receptor NR4A258." (PMID 38704393, 2024). "Curcumin effectively decreases the expression of estrogen-related receptor alpha (ERRα) in osteosarcoma cells." (PMID 34671398, 2021).
melanoma (11 papers, 2011 to 2025). A malignant, usually aggressive tumor composed of atypical, neoplastic melanocytes. "Coherently, in silico analysis of a TCGA melanoma dataset (n = 448 patients) revealed that the expression of LDH‐A, HK2 (encoding gene for HKII) and SLC16A3 (encoding gene for the transporter MCT4) inversely correlate with oestrogen‐related receptor alpha (ERRα), a representative female sex marker." (PMID 39888245, 2025). "Among NRs expressed in >10% of melanoma cells were NR1H3, NR3C1, NR2F6, and ESRRA." (PMID 37406115, 2023).
triple-negative breast carcinoma (11 papers, 2015 to 2024). An invasive breast carcinoma which is negative for expression of estrogen receptor (ER), progesterone receptor (PR), and human epidermal growth factor receptor 2 (HER2). "Previous studies identified a subgroup of triple-negative breast cancer patients with high expression of estrogen related receptor alpha (ERRα) that has better prognosis when treated with tamoxifen." (PMID 37163498, 2023). "Increased expression of estrogen-related receptor alpha (ERRα), an orphan nuclear factor and a master regulator of cellular energy metabolism, is seen in ERα-negative breast cancer and triple-negative breast cancer (TNBC)." (PMID 39749216, 2024). "Interestingly, miR-497 has been also reported to target estrogen-related receptor alpha (ERRα), a nuclear receptor overexpressed in ERα negative breast cancer; downregulation of miR-497 is then responsible for ERRα induction and increased proliferation of triple-negative breast cancer cells." (PMID 32626702, 2020).
colorectal cancer (10 papers, 2013 to 2022). A primary or metastatic malignant neoplasm that affects the colon or rectum. "We have previously shown that PGC-1βand the transcription factor, Estrogen-Related Receptor Alpha (ERRα), are upregulated in colorectal cancer (CRC) in response to K-Ras mutations and that depletion of either protein decreases growth in vitro and in vivo." (PMID 36230802, 2022). "In addition, the estrogen-related receptor alpha (ERRα) has been implicated in the regulation of OPN expression in human colorectal cancer." (PMID 34359694, 2021). "Peroxisome Proliferator-Activated Receptor Gamma, Coactivator 1 Beta (PGC-1β) and Estrogen-Related Receptor Alpha (ERRα) are proteins that are over-expressed to support the survival of colorectal cancer (CRC) cells, but the details of how they promote the growth of CRC has not been defined." (PMID 36230802, 2022). "In this study, we found that estrogen-related receptor alpha (ERRα, also called NR3B1) binds to OTUB1 promoter and regulates its expression in colorectal cancer." (PMID 31737118, 2019).
Insulin resistance (10 papers, 2012 to 2025). Increased resistance towards insulin, that is, diminished effectiveness of insulin in reducing blood glucose levels. "Therefore, ESRRA activation may be beneficial in regulating insulin resistance, fatty acid oxidation/oxidative phosphorylation, and hepatic glucose production from gluconeogenesis in diabetic patients." (PMID 32121253, 2020). "In mice fed a high-fat diet, insulin resistance activates PGC-1α and estrogen-related receptor alpha (ERRα), which bind to the PDK4 promoter, enhancing its mRNA and protein expression." (PMID 39966707, 2025).
lung carcinoma (10 papers, 2013 to 2023). "The mRNA levels of FNDC5 and ESRRA (encoding ERRα) were assessed in IMR-90 cells after co-culture with lung cancer cells." (PMID 36430689, 2022). "Normal fibroblasts revealed an upregulation of the FNDC5 and ESRRA genes under the influence of lung cancer cells." (PMID 36430689, 2022). "The expression levels of the ESRRA gene in IMR-90 cells after co-culture with cells of the lung cancer line were also analyzed compared to the control." (PMID 36430689, 2022). "We also noticed a change in ESRRA gene expression, which was also increased in normal fibroblasts after 48 h incubation with lung cancer cells." (PMID 36430689, 2022). "Changes in the expression level of the FNDC5 and ESRRA genes in fibroblasts simulating the lung tumor stroma after incubation with lung cancer cells have been described for the first time." (PMID 36430689, 2022). "One of the objectives was to verify whether the expression of FNDC5 and ESRRA genes increased in stromal cells due to the presence of lung cancer cells." (PMID 36430689, 2022). "The conducted experiment in an in vitro model indicated that the presence of lung cancer cells could induce an increase in the expression of the FNDC5 and ESRRA genes in stromal fibroblasts." (PMID 36430689, 2022). "However, there have been no in vitro studies to determine the impact of lung cancer cells on changes in the level of FNDC5 or ESRRA expression in lung fibroblasts." (PMID 36430689, 2022).
osteoporosis (10 papers, 2009 to 2024). A condition of reduced bone mass, with decreased cortical thickness and a decrease in the number and size of the trabeculae of cancellous bone (but normal chemical composition), resulting in increased fracture incidence. "For example, one study reported that Cordyceps militaris had antimetastatic effects by inhibiting estrogen-related receptor alpha (ERRα); on the other hand, another study reported that Cordyceps sinensis alleviated osteoporosis induced by estrogen deficiency." (PMID 35550138, 2022).
bladder cancer (6 papers, 2021 to 2025). "The impact of estrogen-related receptor alpha (ERRα), a nuclear receptor sharing structural and functional properties with ERs, on bladder cancer has also been assessed." (PMID 40486871, 2025).
cardiac hypertrophy (6 papers, 2019 to 2022). "Furthermore, anti-miR-199a attenuates cardiac hypertrophy and restores cardiac function in vivo through the PPARGC1A (PGC-1α)/ESRRA (ERRα) axis." (PMID 34869689, 2021).
gastric cancer (6 papers, 2013 to 2025). A primary or metastatic malignant neoplasm involving the stomach. "Collectively, our data provide solid evidence that ESRRA play key role in GC progression and development, which suggests that drug targeting ESRRA could be used as a potential therapeutic method for gastric cancer." (PMID 34131395, 2021). "Besides, the transcriptional factor estrogen-related receptor alpha was identified as the most significant and common enriched transcription factor in pan-cancer screen including gastric cancer." (PMID 34131395, 2021). "In addition, ESRRA expression level in gastric cancer with grade T3 and T4 was significantly higher than T1 and T2." (PMID 34131395, 2021). "Based on all the findings above, we hypothesized that ESRRA overexpression in gastric cancer favors GC growth and viability, supports tumor cell invasion and metastatic abilities." (PMID 34131395, 2021). "However, few researches have explored the role of ESRRA plays in gastric cancer." (PMID 34131395, 2021). "ESRRA regulates the CD/CDK1/CyclinB1 pathway through DSN1 and promotes the development of gastric cancer." (PMID 38189879, 2024).
metabolic syndrome (6 papers, 2015 to 2025). A cluster of metabolic risk factors for CARDIOVASCULAR DISEASES and TYPE 2 DIABETES MELLITUS. "In particular, ESRR alpha (ESRRa) and ESRR gamma (ESRRg) are key metabolic regulators of energy homeostasis, and abnormal functions of these proteins are linked to metabolic syndromes including diabetes and fatty liver disease." (PMID 26657540, 2015).
oral squamous cell carcinoma (6 papers, 2018 to 2025). "ESRRA is a transcription factor that is involved in tumorigenesis, such as oral squamous cell carcinoma." (PMID 34504794, 2021). "In oral squamous cell carcinoma and seminoma cells, m6A/IGF2BP1-mediated mRNA stabilization of estrogen-related receptor alpha (ERRα) and transcription factor-activating enhancer-binding protein 2C (TFAP2C) can facilitate tumor cell survival upon cisplatin treatment." (PMID 40584294, 2025).
pancreatic cancer (6 papers, 2020 to 2024). "ESRRA was identified as a prominent differentially expressed gene in both breast and pancreatic cancer samples, and estrogen-related receptor α (ERRα) was found to link miR-1291 and CPT1C." (PMID 32641987, 2020).
lymph node metastasis (5 papers, 2015 to 2024). "Higher ESRRA expression level was related to tumor invasion depth, lymph node metastasis, distant metastasis as well as TNM stage statistic significantly." (PMID 34131395, 2021).
serous ovarian cancer (5 papers, 2011 to 2023). "A fusion transcript presumed to arise from a chromosomal rearrangement involving the ESRRA and C11orf20 genes has previously been described to be present in 15% of serous ovarian carcinomas—the first fusion transcript to be associated with this common and often fatal cancer." (PMID 24504521, 2014). "We evaluated the prevalence of the ESRRA-C11orf20 fusion in a set of 68 patients with serous ovarian cancer, by RT-PCR followed by Sanger sequencing." (PMID 21949640, 2011). "They used deep paired-end sequencing to detect the fusion gene ESRRA–C11orf20 in 10 out of 67 (15%) serous ovarian carcinomas examined, a finding that holds great promise for our understanding of ovarian tumorigenesis as well as, potentially, for new treatment strategies." (PMID 24504521, 2014). "Our findings cast a spotlight on ESRRA as a candidate oncogene in serous ovarian cancer." (PMID 21949640, 2011).
type 2 diabetes (5 papers, 2011 to 2025). "However, expression of ESRRA was unaltered in skeletal muscle of individuals with NGT or type 2 diabetes, suggesting that reduction in PGC-1α is sufficient to impair BCAA expression or, alternatively, the PGC-1α–ERRα interaction is compromised in type 2 diabetes." (PMID 34131782, 2021).
Sepsis (4 papers, 2020 to 2025). Sepsis is defined as life-threatening organ dysfunction caused by a dysregulated host response to infection. "This study aims to investigate the role of estrogen-related receptor alpha (ERRα) in sepsis-induced ALI." (PMID 37340376, 2023). "This study investigated the regulatory role of estrogen-related receptor alpha (ERRα) in an experimental model of sepsis-induced ALI." (PMID 32714486, 2020).
cardiomyopathy (3 papers, 2021 to 2023). A disease of the heart muscle or myocardium proper. "Deletion of ERRα/γ in mice leads to cardiomyopathy with arrested maturation of mitochondria, while ESRRA and ESRRA deletion in human PSC-CMs downregulates expression of non-cardiac genes, including those consistent with a fibroblast phenotype such as TCF21, periostin, and collagen type III." (PMID 33712058, 2021).
cervical cancer (3 papers, 2014 to 2025). A primary or metastatic malignant neoplasm involving the cervix. "Other genes, such as COX6B1 is related to cell apoptosis and ESRRA also have been reported associated with cervical cancer." (PMID 24992025, 2014).
eating disorder (3 papers, 2020 to 2024). A broad group of psychological disorders with abnormal eating behaviors leading to physiological effects from overeating or insufficient food intake. "This regulatory loop may be of clinical relevance, as loss of ESRRA function in brain regions of mice or loss-of-function mutations in humans have been associated with eating disorders." (PMID 31471878, 2020).
neuroblastoma (3 papers, 2016 to 2021). Neuroblastoma (NB) is the most common solid, extracranial childhood tumor. "Indeed, inhibition of ERRα decreases HIF2A mRNA expression and high expression of the ERRα-encoding gene ESRRA significantly correlates with poor overall and progression-free survival in neuroblastoma." (PMID 33809291, 2021).
cancer of the thyroid (2 papers, 2013 to 2023). "Most cancer types showed weak to moderate cytoplasmic positivity of ESRRA proteins compared to cancer of the thyroid and breast." (PMID 37240447, 2023).
myocarditis (2 papers, 2023 to 2024). Myocarditis is a condition that is characterized by inflammation of the heart muscle (myocardium). "When we examined ESRRA mRNA levels by qRT-PCR during myocarditis, we found that ESRRA was significantly decreased in mice with myocarditis compared to controls (p < 0.0001)." (PMID 39696682, 2024). "Similar to PGC1α and NRF1, we found that females had significantly higher levels of ESRRA transcript during myocarditis compared to males (p = 0.0128)." (PMID 39696682, 2024). "Unbiased TRANSFAC analysis identified estrogen-related receptor alpha (ERRα) as a transcription factor that may mediate sex differences in mitochondrial function during myocarditis." (PMID 39696682, 2024). "We found major sex differences in transcriptional programming related to cardiac mitochondrial homeostasis during myocarditis and identified estrogen-related receptor alpha (ERRα) as a transcription factor that may be responsible for mediating the sex difference." (PMID 39696682, 2024).
oncocytic tumors (2 papers, 2009 to 2013). "An independent microarray data set showed the overexpression of ELK1, RUNX1 and ESRRA in the thyroid oncocytic tumours." (PMID 19536094, 2009).
alcohol use disorder (1 paper, 2025). "Whole‐exome sequencing of 83 alcohol use disorder patients identified 106,525 SNVs and 19,826 InDels, revealing six genes (CNTNAP3, ZNF683, ALDH2, CCHCR1, ZNF45, ESRRA) with deleterious mutations through comprehensive bioinformatics analysis." (PMID 40730494, 2025).
anaplastic astrocytoma (1 paper, 2021). "In detail, one patient collected tumor specimens in all stages of MT in the present cohort.PRKCQ,PPIF,NRP1,MEFV,GGT1,FAN1, andBTKmutations were found in both DA and anaplastic astrocytoma, whereas mutations ofTBC1D19,ESRRA,DIAPH2,COG6, andCBWD3occurred in HGA." (PMID 34430964, 2021).
malnutrition (1 paper, 2026). Inadequate nutrition resulting from poor diet, malabsorption, or abnormal nutrient distribution. "Our findings reveal that ESRRA functions as an exercise executor linking metabolism with epigenetic modification, highlighting a gluconeogenic-epigenetic regulatory axis that could be fine-tuned to mitigate risk factors of MASLD/MASH such as aging, menopause, a sedentary lifestyle and malnutrition." (PMID 42104013, 2026).
mesothelioma (1 paper, 2023). A usually malignant and aggressive neoplasm of the mesothelium which is often associated with exposure to asbestos. "Estrogen-related receptor alpha (ERRα) expression can modulate the expression of MCT1 in mice, and the induction of estrogen receptor β (ERβ) expression resulted in increased expression of MCT4 in mesothelioma cells of mice." (PMID 37919807, 2023).
metastatic prostate carcinoma (1 paper, 2025). A carcinoma that arises from the prostate gland and has spread to other anatomic sites. "Results showed that ERRα (ESRRA) and ACO2 manifested a positive expression correlation pattern, whereas ERRα and ZIP1 showed a negative expression correlation pattern in metastatic prostate cancer." (PMID 40044646, 2025).
periapical granuloma (1 paper, 2021). Chronic nonsuppurative inflammation of periapical tissue resulting from irritation following pulp disease or endodontic treatment. "MCODE-1 with the highest significance for nuclear receptor transcription pathway and the highest PPI in periapical granuloma was between RXRA, PPARG, ESR1, ESRRA, and NR0B1 proteins." (PMID 34539639, 2021). "PPI revealed the relation between ESR1, ESRRA, and NR0B1 to periapical granuloma." (PMID 34539639, 2021).
proctitis (1 paper, 2025). An inflammatory process affecting the anus. "Based on previous findings related to the pathogenesis of radiation-induced proctitis, we investigated the expression of ESRRA protein in the rectal tissues of patients to determine its clinical significance." (PMID 40827662, 2025).
psoriasis (1 paper, 2024). An autoimmune condition characterized by red, well-delineated plaques with silvery scales that are usually on the extensor surfaces and scalp. "LncRNA AGXT2L1-2 was found to facilitate keratinocytes proliferation and inhibits apoptosis by interacting with estrogen-related receptor alpha in psoriasis." (PMID 38848163, 2024).
Renal cyst (1 paper, 2024). A fluid filled sac in the kidney. "Concordantly, the genes encoding PPARα and estrogen-related receptors (PPARGC1A, PPARA, ESRRA and ESRRG) were all downregulated in renal cysts." (PMID 39000280, 2024).